FIBIN (fin bud initiation factor homolog)
Synonyms: MGC24932
Tractability: Antibody: UniProt places it where antibodies can reach, with medium confidence; UniProt predicts a signal peptide or a membrane-spanning region; its Gene Ontology location is reachable by antibodies, with medium confidence.
Gene: Protein-coding gene on chromosome 11 (26,994,112 to 26,997,087, forward strand). Ensembl gene ENSG00000176971.
Subcellular location: Secreted; Golgi apparatus; Endoplasmic reticulum
Gene Ontology:
Molecular function: protein homodimerization activity
Cellular component: endoplasmic reticulum; extracellular region; Golgi apparatus
Genetic constraint (gnomAD): Loss-of-function variants: 8 observed, 13.18 expected, observed/expected ratio (o/e) 0.61, 90% interval 0.35 to 1.1. The upper end of that interval is the gene's LOEUF score, 1.1, which puts it in group 4 of 6, group 1 being the genes least tolerant of losing a copy. Missense variants: 261 observed, 273.91 expected, observed/expected ratio (o/e) 0.95, 90% interval 0.86 to 1.06. Synonymous variants: 127 observed, 120.51 expected, observed/expected ratio (o/e) 1.05, 90% interval 0.91 to 1.22.
Homologues: Orthologues: macaque FIBIN (99% identical), pig FIBIN (97% identical), rabbit FIBIN (96% identical), mouse Fibin (93% identical), rat Fibin (92% identical), guinea pig FIBIN (86% identical), dog FIBIN (75% identical), tropical clawed frog fibin (64% identical), zebrafish fibinb (61% identical), zebrafish fibina (55% identical).
Diseases named in the same sentence as FIBIN in open-access papers:
FIBIN is named in the same sentence as 9 diseases in open-access papers, as found by Europe PMC text mining. Sharing a sentence is not in itself a finding about the gene and the disease. The quoted sentences say what the papers report.
Hypertension (1 paper, 2023). The presence of chronic increased pressure in the systemic arterial system. "Furthermore, PIK3C2G, FIBIN, CHRNA1, NPNT, MEOX1, and POU2F2 linked obesity and lung cancer, while PTPRQ, SSUH2, CILP2, CDH2, ABCA12, CPXM1, and L1CAM linked hypertension and lung cancer." (PMID 36685671, 2023).
osteosarcoma (1 paper, 2022). A usually aggressive malignant bone-forming mesenchymal neoplasm, predominantly affecting adolescents and young adults. "Given that this gene was found to be differentially expressed in primary/metastatic osteosarcoma cell line pairs, and that it can be used for survival prediction in the present study, further examination of FIBIN in osteosarcoma may provide insights into its function." (PMID 35887382, 2022).
psychiatric disorder (1 paper, 2017). A disorder characterized by behavioral and/or psychological abnormalities, often accompanied by physical symptoms. "Our study provides evidence that the same genes (e.g., MC4R, FIBIN, and FMO5) harbor both common and rare variants affecting body size and that anthropometric traits share genetic loci with developmental and psychiatric disorders." (PMID 28963451, 2017).
tumor (1 paper, 2016). "The remaining two down-regulated genes, BBOX and FIBIN, were mapped in a homozygous 11p13 deletion detected in a single tumor." (PMID 26913079, 2016). "Another validated focal CNA detected in one tumor (WT201) was the 825 kb homozygous deletion at 11p14.1p14.2 (#chr11:26,688,179-27,513,817; GRCh37), harbouring BBOX, among others genes (SLC5A12, FIBIN, CCDC34, LGR4)." (PMID 26913079, 2016).
FIBIN also shares sentences with these, for which no sentence is quoted: atherosclerosis (1 paper); cancer (1); cardiovascular disease (1); lung carcinoma (1); Obesity (1).